ENSG00000252888
Gene: Small nucleolar RNA gene on chromosome 10 (76,835,377 to 76,835,502, reverse strand). Ensembl gene ENSG00000252888.
Homologues: Paralogues in human: SNORA31B (78% identical), SNORA31 (60% identical).